SLC15A4 (solute carrier family 15 member 4)
Diseases named in the same sentence as SLC15A4 in open-access papers (continued):
Sharing a sentence is not in itself a finding about the gene and the disease.
lung adenocarcinoma (1 paper, 2021). A carcinoma that arises from the lung and is characterized by the presence of malignant glandular epithelial cells. "According to our study, more investigations should be performed to validate SLC15A4 as a novel indicator or drug target for lung adenocarcinoma in translational medicine." (PMID 34168674, 2021). "For SLC15A4, the expression in lung adenocarcinoma (30 study cases) was much higher than that in lung squamous cell carcinoma (149 study cases)." (PMID 34168674, 2021). "In lung adenocarcinoma, the representative staining of SLC15A4 was weak in the nucleus and cytoplasm." (PMID 34168674, 2021). "According to our KM overall survival analysis, SLC15A4 is sensitive and is considered a prognostic biomarker in lung adenocarcinoma." (PMID 34168674, 2021). "Briefly, all genes in SLC15A family could be used as clinical outcome prediction biomarkers in NSCLS, while SLC15A2 and SLC15A4 are with favorable prognostic value in lung adenocarcinoma." (PMID 34168674, 2021). "Taken together, our findings clearly demonstrated that SLC15A4 could be an ideal lung adenocarcinoma prognostic marker and could be further targeted." (PMID 34168674, 2021). "Only SLC15A2 and SLC15A4 were suitable to predict the clinical outcome of lung adenocarcinoma." (PMID 34168674, 2021). "However, more studies including large patient cohorts are required to validate the clinical utility of SLC15A4 in lung adenocarcinoma." (PMID 34168674, 2021). "SLC15A4 could be used as a survival prediction biomarker for lung adenocarcinoma due to its potential role in cell division regulation." (PMID 34168674, 2021). "Moreover, the IHC staining pattern of SLC15A4 in lung adenocarcinoma may help clinicians predict clinical outcomes." (PMID 34168674, 2021). "Our results clearly showed that only SLC15A2 and SLC15A4 could be used as clinical outcome prediction biomarkers for overall survival rate in lung adenocarcinoma with HR = 0.57 (0.45–0.72); log rank P-value = 2.5e-06 and HR = 0.4 (0.38–0.62); log rank P-value = 8.7e-09, respectively." (PMID 34168674, 2021). "Although all family members exhibited an association with the clinical outcomes of patients with NSCLC, we found that none of them could be used for squamous cell carcinoma of the lung and that SLC15A2 and SLC15A4 could serve as biomarkers for lung adenocarcinoma." (PMID 34168674, 2021).
ovarian carcinoma (1 paper, 2021). A malignant neoplasm originating from the surface ovarian epithelium. "Notably, SLC15A4 is hypermethylated in A2780CP cells, indicating its role in chemotherapy for ovarian cancer." (PMID 34168674, 2021).
peritonitis (1 paper, 2018). Inflammation of the peritoneum (tissue that lines the abdominal wall and covers most of the organs in the abdomen). "Because of the similarity between SLC15A3 and SLC15A4, we aimed to identify whether the expression of SLC15A3 was changed in mice with peritonitis induced by E.coli." (PMID 29991810, 2018).
Psoriasiform dermatitis (1 paper, 2018). A skin abnormality characterized by redness and irritation, with thick, red skin that displays flaky, silver-white patches (scales). "Therefore, we hypothesized that studying slc15a4 deficiency in the IMQ psoriasiform dermatitis model may clarify the role of the TLR7-pDC-IFN-I pathway of immune pathology." (PMID 30262916, 2018). "Therefore, we hypothesized that studying slc15a4 deficiency in the IMQ-induced psoriasiform dermatitis model may serve as an alternative strategy to specifically disrupt this pathway." (PMID 30262916, 2018). "Here we extend our analysis of slc15a4 to examine its role in psoriasiform dermatitis mediated by the canonical TLR7 agonist imiquimod as compared to intradermal IL23 injection." (PMID 30262916, 2018). "To determine the specificity of slc15a4 in this psoriasiform model, we executed a more chronic model of psoriasiform dermatitis that activates the downstream inflammatory cascade by direct intralesional injection of IL23 which promotes Th17 skewing." (PMID 30262916, 2018). "Here, we evaluated the role of slc15a4 in imiquimod-induced psoriasiform dermatitis." (PMID 30262916, 2018). "Taken together, we have identified a role for slc15a4 but not canonical psoriasiform genes in the imiquimod model of psoriasiform dermatitis." (PMID 30262916, 2018).
thrombosis (1 paper, 2024). "Among them, mutations in ABCA13, FLT1, NRP1, SWAP70 and SLC15A4 are strongly associated with immunity or proliferation, whereas mutations in VWF, SELP and EPHB2 are associated mainly with thrombosis." (PMID 39671267, 2024). "On the other hand, SLE, like PNH, is characterised by complement activation and thrombogenesis, which can explain, to some extent, our finding that patients with thrombosis are likely to have higher SLC15A4 or ABCA13 mutation incidence than patients without thrombosis." (PMID 39671267, 2024). "In addition, we found that a greater proportion of patients with thrombosis than patients without thrombosis carried EpHB2 mutations (p = 0.015), SWAP70 mutations (p = 0.039), ABCA13 mutations (p = 0.01) and SLC15A4 mutations (p = 0.004)." (PMID 39671267, 2024).
uterine cancer (1 paper, 2022). Primary or metastatic malignant neoplasm involving the uterine corpus and/or the cervix. "Regarding the overall somatic alteration frequency in all listed cancers, SLC15A4 showed a generally higher frequency with up to 5.48% in uterine cancer (Online Resource 2a), whereas the maximum alteration frequency of the PTGES gene was only 1.7%, also in uterine cancer (Online Resource 2b)." (PMID 35562597, 2022).
tumor (5 papers, 2001 to 2023). "SLC15A4 is required for Toll-like receptor 7 (TLR7)- and TLR9-mediated type I interferon (IFN-I) production in plasmacytoid dendritic cells (pDCs) by the mTOR pathway, highlighting its role in regulating the immune response in the tumor microenvironment." (PMID 34168674, 2021).
cancer (3 papers, 2021 to 2023). A tumor composed of atypical neoplastic, often pleomorphic cells that invade other tissues. "Further validation of the identified variants has been provided by the large-scale WES data of UK Biobank, reporting statistically significant gene-phenotype associations of the SLC15A4 gene and the clinical phenotypes of malignant neoplasms in the colon and rectum." (PMID 35562597, 2022). "Thus, we hope to facilitate a better understanding of the identified upstream variant in the context of SLC15A4 gene regulation in particular and of the postulated synergistic model of coding and non-coding variants in cancer predisposition in general." (PMID 35562597, 2022). "By identifying and analyzing an additional variant in the upstream region of the SLC15A4 gene showing the same familial segregation, we aimed to expand the theory of high-penetrance monogenic inheritance to a synergistic model of coding and non-coding variants underlying cancer predisposition." (PMID 35562597, 2022). "Unlike SLC15A1 and SLC15A2, which are frequently studied in the cancer field, the roles of SLC15A3 and SLC15A4 in cancer are quite opaque." (PMID 34168674, 2021). "More importantly, the regulation of SLC15A4 transportation activities is also promising for anti-cancer research." (PMID 34168674, 2021). "As SLC15A2 RNA-seq expression is ultra-low and intensively studied in cancer, we aimed to reveal more molecular functions of SLC15A4." (PMID 34168674, 2021). "SLC15A family members from SLC15A1 to SLC15A4 were searched in 20 major cancers through the Oncomine database." (PMID 34168674, 2021). "Our results show that SLC15A4 mainly participated in the cell cycle and division, implying its role in cancer proliferation." (PMID 34168674, 2021). "The IHC staining pattern showed that the SLC15A4 protein level could be distinguished by a pathologist, as the patients may have strong membrane staining and strong cytoplasmic intensity in the cancer cells." (PMID 34168674, 2021). "It draws attention that the dipeptide-mimetic bestatin, which is known as an anti-cancer substrate transported by SLC15A4, may enhance its function via up-regulating SLC15A4 activity." (PMID 34168674, 2021). "For SLC15A4, only a few studies have shown a very limited understanding of its functions in cancer." (PMID 34168674, 2021). "These pathway enrichments highlight that SLC15A4 may have major functions through peptide intake to control the cell cycle, which directly exerts a phenotype in cancer cell proliferation." (PMID 34168674, 2021). "It is crucial to intensively explore the role of SLC15A4 in malignancies, as the understanding of SLC15A4 in cancer is quite limited, and its physiological and pharmacological status is unknown." (PMID 34168674, 2021). "According to our selection standard for those cancers with unique analysis, the studies included were SLC15A1 (7:24), SLC15A2 (13:48), SLC15A3 (27:13), and SLC15A4 (12:3)." (PMID 34168674, 2021). "SLC15A3 and SLC15A4 were different from SLC15A1 and SLC15A2, with increased patterns in pan-cancer compared with normal tissue." (PMID 34168674, 2021). "SLC15A2 had a controversial expression pattern with SLC15A3 across the pan-cancer study, where SLC15A1 showed a down-regulated expression in most of solid cancers and SLC15A4 displayed an up-regulated pattern." (PMID 34168674, 2021).
renal disease (1 paper, 2021). "Furthermore, given the minimal induction of renal disease, we were unable to establish a potential therapeutic benefit conferred by slc15a4 deficiency in this model." (PMID 33444326, 2021).
SLC15A4 also shares sentences with these, for which no sentence is quoted: immune dysfunction (2 papers); lupus nephritis (2); autism (1); breast carcinoma (1); Crohn disease (1); infection (1); inflammation (1); melanoma (1); metastatic prostate carcinoma (1); nephritis (1); rheumatoid arthritis (1); Sjögren's syndrome (1); squamous cell carcinoma (1); squamous cell carcinoma of the lung (1).